ZBED3 (zinc finger BED-type containing 3)
Description:
Acts as a positive regulator in the activation of the canonical Wnt/beta-catenin signaling pathway by stabilizing cytoplasmic beta-catenin (By similarity). Involved in transcription activation of Wnt target gene expression (By similarity). Plays a role in symmetric division of blastomeres in the early stages of embryogenesis via regulation of mitotic spindle central positioning and organization of the F-actin filament network (By similarity). Plays a role in regulating the distribution of cellular organelles, via modulation of cytoskeletal dynamics and cytoplasmic lattice formation (By similarity).
Synonyms: MGC15435
Tractability: Antibody: UniProt places it where antibodies can reach, with high confidence; its Gene Ontology location is reachable by antibodies, with medium confidence; the Human Protein Atlas places it where antibodies can reach.
Gene: Protein-coding gene on chromosome 5 (77,072,072 to 77,087,353, reverse strand). Ensembl gene ENSG00000132846.
Subcellular location: Cytoplasm; Membrane; Secreted
Subcellular location (Human Protein Atlas): Plasma membrane; Nucleoplasm; Predicted to be secreted
Gene Ontology:
Molecular function: DNA-binding transcription factor activity; DNA-binding transcription factor activity, RNA polymerase II-specific; RNA polymerase II transcription regulatory region sequence-specific DNA binding; DNA binding
Biological process: response to glucose; response to insulin; actin filament organization; endoplasmic reticulum localization; establishment of spindle localization; mitochondrion localization; negative regulation of protein phosphorylation; positive regulation of canonical Wnt signaling pathway; positive regulation of embryonic development; positive regulation of transcription by RNA polymerase II; protein stabilization
Cellular component: extracellular region; chromatin; cytoplasm; cytosol; membrane; nucleus
Genetic constraint (gnomAD): Loss-of-function variants: 2 observed, 0.73 expected, observed/expected ratio (o/e) 2.74. That is too few expected variants to judge how well the gene tolerates losing a copy. Missense variants: 384 observed, 204.01 expected, observed/expected ratio (o/e) 1.88, 90% interval 1.73 to 1.98. Synonymous variants: 173 observed, 93.1 expected, observed/expected ratio (o/e) 1.86, 90% interval 1.63 to 1.98.
Homologues: Orthologues: chimpanzee ZBED3 (98% identical), macaque ZBED3 (92% identical), dog ZBED3 (58% identical), rat Zbed3 (54% identical), mouse Zbed3 (51% identical).
Diseases named in the same sentence as ZBED3 in open-access papers:
ZBED3 is named in the same sentence as 15 diseases in open-access papers, as found by Europe PMC text mining. Sharing a sentence is not in itself a finding about the gene and the disease. The quoted sentences say what the papers report.
diabetes (4 papers, 2015 to 2022). "Others have been associated with diabetes (ZBED3), asthma (EMID2), and cancer (FBXO3, HOOK2, MT2A, EIF3E, RPH3AL, PTRF, MT1M, STK32A)." (PMID 25748564, 2015). "Obesity is one of the important causes of diabetes, so we studied the role of ZBED3 in adipogenesis and found that ZBED3 expression increased gradually during hADSC adipogenic differentiation and have positive impact on this process, which was consistent with lnc13728." (PMID 33712067, 2021). "Thus, genetic variation at ZBED3 could in theory contribute to diabetes risk via multiple cell-specific processes." (PMID 31754873, 2019).
lung carcinoma (3 papers, 2019 to 2024). "ZBED3, which positively regulates Wnt/β-catenin signaling by enhancing β-catenin expression, thereby promoting the proliferation and invasiveness of lung cancer, was selected for subsequent experimentation." (PMID 38182896, 2024). "In lung cancer, ZBED3 exhibits significant upregulation in tumor tissues compared with normal tissues." (PMID 38182896, 2024). "Here, we investigated Zbed3's ability to promote lung cancer cell proliferation and invasion and the involvement of the Axin/TPC/glycogen synthase kinase 3β (Gsk‐3β) complex to the response." (PMID 30417576, 2019). "In A549 and H1299 lung cancer cells, Zbed3 overexpression promoted cancer cell proliferation and invasiveness, as well as Wnt signalling and expression of downstream mediators, including β‐catenin, cyclin D1 and MMP7 (P < 0.05)." (PMID 30417576, 2019). "Colony formation and MTT assays showed that transfecting lung cancer cells with wild‐type Zbed3 significantly enhanced their proliferation, but that effect was largely inhibited by transfection of the Zbed3 mutant lacking an Axin binding sited." (PMID 30417576, 2019). "Our previous work showed that Zbed3 is overexpressed in nonsmall cell lung cancer and that down‐regulation of Zbed3 inhibited β‐catenin expression and cancer cell proliferation and invasiveness." (PMID 30417576, 2019). "Notably, ZBED3 also participates in the development of various cancer types, with lung cancer being the most comprehensively investigated." (PMID 38182896, 2024). "Additionally, ZBED3 promotes lung cancer cell proliferation by regulating the expression of proliferating cell nuclear antigen." (PMID 38182896, 2024). "Moreover, other zinc finger BED-type transcription factors, such as ZBED3 and ZBED6, are implicated in cancer progression in lung cancer cells and colorectal cancer cells, respectively." (PMID 35052473, 2022). "We first assessed expression of several Zbed3 and Wnt signalling molecules, including Axin, GSK‐3β, and β‐catenin in A549 and NCI‐H1299 lung cancer cells." (PMID 30417576, 2019).
colorectal cancer (2 papers, 2022 to 2024). A primary or metastatic malignant neoplasm that affects the colon or rectum. "Furthermore, an established prognostic model for colorectal cancer, incorporating eight genes, including ZBED3, revealed a negative correlation between ZBED3 expression and clinical risk scores." (PMID 38182896, 2024).
Insulin resistance (2 papers, 2021 to 2025). Increased resistance towards insulin, that is, diminished effectiveness of insulin in reducing blood glucose levels. "It was reported that ZBED3 mRNA and protein in muscle and fat were significantly increased in both db/db mice and T2DM patients and associated with insulin resistance." (PMID 33712067, 2021).
type 2 diabetes (2 papers, 2011 to 2016). "Of the WNT-annotated SNPs (in genes upstream of TCF7L2), we found, in addition to TCF7L2, the SNPs in NOTCH2 and ZBED3 loci to significantly interact with fiber intake on type 2 diabetes incidence." (PMID 27551309, 2016). "SNPs in TCF7L2, NOTCH2, and ZBED3 showed significant interactions with fiber intake on type 2 diabetes incidence (Pinteraction = 0.034, 0.005, 0.017, and 0.002, respectively)." (PMID 27551309, 2016). "Another interaction was observed between quintiles of fiber intake and ZBED3 rs4457053 on type 2 diabetes incidence (Pinteraction = 0.002)." (PMID 27551309, 2016). "Higher fiber associated with lower type 2 diabetes risk only among risk allele carriers of the NOTCH2 variant and homozygotes of the risk allele of the ZBED3 variant." (PMID 27551309, 2016). "Higher fiber intake was observed to associate with lower incidence of type 2 diabetes only among risk allele carriers of the NOTCH2 variant and homozygotes for the risk allele of the ZBED3 variant." (PMID 27551309, 2016). "In addition, novel interactions between dietary fiber intake and two type 2 diabetes-associated variants in the NOTCH2 and ZBED3 loci were observed." (PMID 27551309, 2016).
depression (1 paper, 2023). "Other genes near the variant also showed involvement in brain development (ZBED3), in GABAergic interneurons in the prefrontal cortex, hippocampal abnormalities, depression, and other neuropsychiatric disorders such as substance abuse (CRHBP)." (PMID 37337823, 2023).
female infertility (1 paper, 2022). Diminished or absent ability of a female to achieve conception. "Mutations in OOEP and ZBED3, components of the SCMC, have not previously been associated with human female infertility." (PMID 35946397, 2022).
gastric cancer (1 paper, 2024). A primary or metastatic malignant neoplasm involving the stomach. "However, in gastric cancer, ZBED3 overexpression has been found to alleviate the malignant phenotype, suggesting a tumor-suppressing role." (PMID 38182896, 2024).
lymph node metastasis (1 paper, 2024). "Furthermore, ZBED3 displays significant correlations with various clinical parameters, including enhanced lymph node metastasis, advanced TNM stages, elevated Ki67 expression, and unfavorable clinical outcomes." (PMID 38182896, 2024).
cancer (7 papers, 2015 to 2024). A tumor composed of atypical neoplastic, often pleomorphic cells that invade other tissues. "The upregulated expression of Nucleolin, Prkcsh, Prkar2b, and Zbed3 and the downregulated expression of Nfatc4 promoted cancer cell proliferation, migration, and invasion by activating the Wnt/β-Catenin signaling pathway." (PMID 34848840, 2021). "When we transfected cells with a Zbed3 mutant lacking an Axin binding site, we found that the mutant promoted cancer cell proliferation and invasiveness to some degree, but the effect was much smaller than that elicited by wild‐type Zbed3." (PMID 30417576, 2019). "Transfection of wild‐type Zbed3 also significantly up‐regulated p120ctn‐1 expression, whereas this ability was also significantly inhibited when transfected with mutant Zbed3 in cancer cells." (PMID 30417576, 2019). "Overexpression of Zbed3 significantly increased β‐catenin expression and Wnt signalling in these cancer cells, as well as their proliferation and invasiveness." (PMID 30417576, 2019). "These discordant findings underscore the distinct roles of ZBED3 in different cancer types." (PMID 38182896, 2024). "Interestingly, the most significantly upregulated genes in Ppm1dT/+ AML (Zbed3, Runx3, Marcks, Extl3, Pcbp4, Igf2bp3, Plch1, and Gdf6) were previously associated with AML and cancer progression." (PMID 37709843, 2023). "Moreover, MTT assays showed that Zbed3 overexpression significantly enhanced cancer cell proliferation, and Transwell assays showed it also enhanced the invasiveness of cancer cells." (PMID 30417576, 2019). "In addition, Transwell assays showed that transfection of wild‐type Zbed3 significantly increased the invasiveness of cancer cells, but again that effect was largely inhibited transfection of the Zbed3 mutant." (PMID 30417576, 2019). "Given that overexpression of the Zbed3 mutant promoted cancer cell proliferation and invasiveness to a small degree, we suggest Zbed3‐mediated enhancement of cancer cell proliferation and invasiveness is in large part, but not entirely, dependent on the function of Axin." (PMID 30417576, 2019). "Current studies showed that ZBED3 is related to the WNT/β-catenin pathway in tumor cells and that promotes cancer proliferation by regulating β-catenin expression by interacting with Axin." (PMID 33712067, 2021). "In contrast, the Zbed3 mutant failed to enhance β‐catenin expression (P > 0.05), and its ability to promote cancer cell proliferation and invasiveness was much less than wild‐type Zbed3 (P < 0.05)." (PMID 30417576, 2019).
tumor (4 papers, 2019 to 2024). "Our experiments indicated that overexpressing ZBED3 reinstates the tumor-suppressive effects observed upon NSUN5 knockdown in Huh7 and Hep 3B cells." (PMID 38182896, 2024). "In vivo study shows that the size of subcutaneously injected tumours were increased in the wild‐type Zbed3 group as compared with the control group, but the effect was largely inhibited by transfection of the Zbed3 mutant." (PMID 30417576, 2019). "Additionally, we found that the overexpression of ZBED3 counteracted the tumor-suppressing effect of NSUN5 knockdown and simultaneously reversed the inhibition of the Wnt/β-catenin signaling pathway." (PMID 38182896, 2024). "In addition, ZBED3 overexpression almost completely reversed the tumor-suppressive effect induced by NSUN5 knockdown." (PMID 38182896, 2024). "Similarly, downregulated genes identified in Cluster 1 have been previously associated with more aggressive tumor characteristics and higher tumor grade; these include RNF39, ADAMTS8, SLC25A42, ST3GAL5, and ZBED3." (PMID 39766155, 2024). "We explored that ZBED3 negatively regulated WNT/β-catenin pathway during hADSC adipogenic differentiation, which appears inconsistent with its function in previous research on tumor cells." (PMID 33712067, 2021).
ZBED3 also shares sentences with these, for which no sentence is quoted: asthma (1 paper); hepatocellular carcinoma (1); Obesity (1); substance abuse (1).